DCN (decorin)
Diseases named in the same sentence as DCN in open-access papers (continued):
Sharing a sentence is not in itself a finding about the gene and the disease.
Insulin resistance (5 papers, 2013 to 2025). Increased resistance towards insulin, that is, diminished effectiveness of insulin in reducing blood glucose levels. "Previous reports have showed elevated decorin gene expression coupled with increased circulating insulin levels and insulin resistance in rodents and humans." (PMID 30874564, 2019). "On the other hand, studies have postulated that decorin is involved in anti-inflammatory processes, due to its binding to Complement C1q and its ability to inhibit Cq1-induced insulin resistance in the adipose tissue of obese rodents." (PMID 31258482, 2019). "Thus, an effect of decorin knockout on pro-coagulation cascades may have contributed to the increased diet-induced insulin resistance in these mice." (PMID 30874564, 2019).
lung adenocarcinoma (5 papers, 2020 to 2022). A carcinoma that arises from the lung and is characterized by the presence of malignant glandular epithelial cells. "In lung adenocarcinoma, DCN is downregulated in tissues and suppresses the proliferation of lung adenocarcinoma cells." (PMID 35420507, 2022). "This suggested that LINC02126 may play important roles in the development of lung adenocarcinoma by regulating the expression of DCN, COX7A1, PLAC9, LUM and MFAP4." (PMID 36357869, 2022). "Hypomethylated and highly expression of DCN are related to poor prognosis in lung adenocarcinoma." (PMID 36357869, 2022). "Decorin (DCN) was proved to be a promising predictive biomarker for the occurrence and prognosis of lung adenocarcinoma by bioinformatics analyses and experiments." (PMID 35300639, 2022). "However, as revealed by a cell proliferation assay, the over-expression of DCN and CAV1 markedly suppresses NSCLC cell proliferation, its role in invasion and migration of lung adenocarcinoma needs further study." (PMID 33870858, 2021).
neuroblastoma (5 papers, 2018 to 2024). Neuroblastoma (NB) is the most common solid, extracranial childhood tumor. "For example, nuclear factor kappa B-induced upregulation of BGN was found to reduce the nitric oxide-induced apoptosis of human neuroblastoma cells, while DCN has been demonstrated to exert protection against hydrogen peroxide-induced apoptosis of retinal pigment epithelial cells." (PMID 38786104, 2024).
non-small cell lung carcinoma (5 papers, 2011 to 2025). A group of at least three distinct histological types of lung cancer, including non-small cell squamous cell carcinoma, adenocarcinoma, and large cell carcinoma. "Epigenetic regulation is an important mechanism underlying the gene expression in aging, and has been shown to regulate DCN expression in non-small cell lung cancer cells." (PMID 33257596, 2020). "Invasion and transfer of non-small cell lung cancer may be inhibited by DCN through the TGF-β signaling pathway." (PMID 40464853, 2025).
oral cancer (5 papers, 2011 to 2019). "In an oral cancer model, decorin was aberrantly expressed in the cancer cells, and knockdown of decorin reduced angiogenic mediators, including VEGF and MMP9, and decreased angiogenesis." (PMID 28290552, 2017). "Decorin was noted in the cytoplasm as well as in the nuclei of human oral cancer biopsies and cell lines." (PMID 24499526, 2013). "In an effort to examine the role of this nuclear localized decorin, we stably knocked down nuclear decorin in this oral cancer cell line model." (PMID 22507529, 2012). "We have used in vitro stable gene silencing in human dysplastic and malignant oral epithelial cells to study the role of nuclear localized decorin in oral cancer angiogenesis." (PMID 22507529, 2012). "The objective of this study was to further examine the effects of nuclear decorin silencing on angiogenesis and angiogenesis related mediators in this oral cancer progression cell line model." (PMID 22507529, 2012). "In this study we used shRNA expression plasmid mediated in vitro stable gene silencing in DOK and SCC-25 cells to study the role of nuclear localized decorin in oral cancer." (PMID 21958730, 2011). "In our previous studies of oral precancerous and cancerous lesions and cellular models of oral cancer progression, we demonstrated that decorin is aberrantly expressed and localized in the nucleus in the dysplastic and malignant oral epithelial cells." (PMID 21958730, 2011). "In search of a possible mechanism by which decorin is aberrantly localized in the nucleus, we sought out to determine if nuclear decorin interacts with nuclear EGFR in our oral cancer model." (PMID 21958730, 2011). "Together, results from our study suggest the importance of decorin as a potential therapeutic target in oral cancer, as it modulates migration and invasion of premalignant and malignant oral epithelial cells." (PMID 21958730, 2011). "Elucidation of potential interactions of the aberrant decorin expressed in the oral cancer progression model and its biological implications need to be addressed further." (PMID 21958730, 2011). "The results of our study highlight the importance of decorin as a potential oral cancer specific therapeutic target." (PMID 21958730, 2011). "Using shRNA expression plasmid mediated in vitro stable gene silencing in dysplastic and malignant oral epithelial cells; we present here a study of the role of nuclear localized decorin in oral cancer progression." (PMID 21958730, 2011). "This indicates a possible means by which decorin is aberrantly localized in the nuclei in our oral cancer model." (PMID 21958730, 2011). "Studies in our laboratory are underway in this direction which will shed light on additional biological aspects of nuclear localized decorin in oral cancer progression." (PMID 21958730, 2011). "We only eliminated this gene because we found no DCN mutations in the sporadic oral cancers examined in the study." (PMID 31798960, 2019). "Taken together, our results indicate that nuclear localized decorin plays an important role in migration and invasion of oral cancer cells and thus may present as a novel potential target for the treatment of oral cancer." (PMID 21958730, 2011). "In this study, we examined the role of nuclear decorin in oral cancer progression." (PMID 21958730, 2011). "Furthermore, we show here that nuclear localized decorin interacts with nuclear EGFR in this oral cancer cell line model." (PMID 21958730, 2011). "Besides decorin-EGFR relation, additional interactions with other nuclear and/or cytosolic factors may result from the aberrant localization of decorin and perhaps result in some of decorin's tumor-promoting role in oral cancer." (PMID 21958730, 2011).
renal carcinoma (5 papers, 2021 to 2025). A carcinoma arising from the epithelium of the renal parenchyma or the renal pelvis. "A study explored the use of an OVs armed with decorin (OAV-Decorin) in combination with CAIX-targeting CAR-T cells for renal cancer treatment." (PMID 41024300, 2025). "In order to improve the efficacy of CAR-T and oncolytic adenovirus in tumor immunosuppressive microenvironment, here we used an oncolytic adenovirus arming decorin (OAV-Decorin) in combination with CAIX-targeting CAR-T for renal cancer cells." (PMID 34977339, 2022). "In vitro, we found that OAV-Decorin combined with CAIX-CAR-T has a strong antitumor effect on renal cancer cells." (PMID 34977339, 2022). "In summary, the CAIX-CAR-T and OAV-Decorin that we constructed proved to have significant specific killing effect on CAIX-positive renal cancer cells in vitro, and the combination usage can further enhance the tumor killing effect." (PMID 34977339, 2022). "Here we combined an oncolytic adenovirus carrying decorin with a CAR-T targeting carbonic anhydrase IX (CAIX) to perform the antitumor activity for renal cancer cells." (PMID 34977339, 2022). "DCN was identified as a renal cancer prognostic marker with lower levels of its protein identified in glomeruli cells of normal kidneys whereas higher levels of SPARC was predicted in glomeruli and lower levels in tubuli cells of normal kidneys." (PMID 34557161, 2021). "Since decorin blocked the activity of TGF-β, our data also identified that OAV-DEC significantly inhibited TGF-β expression on renal cancer cells in tumor tissues from OAV-DEC or OAV-DEC + CAIX-CAR-T treatment, which was identical to other research." (PMID 34977339, 2022). "Compared with the corresponding control groups, higher level of decorin was produced and efficiently released from OAV-DEC-infected renal cancer cells, as detected by ELISA." (PMID 34977339, 2022).
renal cell carcinoma (5 papers, 2020 to 2026). "Additionally, these viruses have been shown to participate in the assembly of the tumor extracellular matrix (ECM) by expressing decorin in a subcutaneous renal cell carcinoma tumor model, thereby improving the tumor immune microenvironment." (PMID 41924602, 2026). "Decorin (DCN), as an important component of the extracellular matrix (ECM), is a small leucine-rich proteoglycan and synthesized by fibroblasts, the deficiency of which promoted renal cell carcinoma growth and metastasis." (PMID 32489319, 2020).
Sepsis (5 papers, 2017 to 2025). Sepsis is defined as life-threatening organ dysfunction caused by a dysregulated host response to infection. "Akkermansia muciniphila protects against sepsis‐associated encephalopathy by reducing hippocampal inflammation and modulating neuronal survival through decorin‐dependent and ‐independent pathways, highlighting its potential as a microbial therapy." (PMID 41186245, 2025). "Previous studies have found that serum DCN level is associated with preterm premature rupture of fetal membranes, acute ischemic stroke, sepsis, and coronary artery disease, suggesting serum DCN level may be used as a biomarker in the diagnosis of various diseases." (PMID 34621191, 2021). "Immunoblot and ELISA analysis revealed increased levels of decorin protein core in patients with sepsis compared to healthy individuals." (PMID 33732235, 2021). "The authors experimentally induced sepsis with LPS in decorin-knockout mice, and they showed that the localization of decorin was in close proximity to macrophage in the lungs." (PMID 33732235, 2021). "Further, decorin expression appears to be transcriptionally up-regulated under conditions of organismal stress (e.g. sepsis and starvation)." (PMID 28798237, 2017). "Notably, AKK not only reduced sepsis‐induced hippocampal inflammation but also upregulated DCN expression, enhanced autophagy in hippocampal CA1 neurons, reduced apoptosis, and ultimately prevented SAE." (PMID 41186245, 2025). "Furthermore, deletion of DCN mitigates the pro-inflammatory cytokine profile in sepsis and sterile inflammatory diseases." (PMID 34621191, 2021). "Our study demonstrates for the first time that in severe sepsis, AKK can directly regulate hippocampal gene expression, upregulate DCN, enhance autophagy, and reduce neuronal apoptosis, highlighting a potential mechanism for its neuroprotective effects." (PMID 41186245, 2025). "If DCN proves protective against SAE, particularly regarding long‐term sepsis prognosis, it may represent a promising therapeutic target." (PMID 41186245, 2025).
type 2 diabetes (5 papers, 2016 to 2026). "In the case-cohort study, decorin (DCN) – one of the best characterized SLRPs – was selected as one of the most important biomarkers for type 2 diabetes prediction." (PMID 38900131, 2024). "Decorin was identified as the most relevant biomarker in type 2 diabetes or obesity-related diseases, but its function in gestational obesity or gestational diabetes mellitus (GDM) remains unknown." (PMID 41876836, 2026). "In the present study, we investigated the effects of decorin (DCN) gene therapy on left ventricular function, cardiac inflammation and fibrosis in type 2 diabetes." (PMID 33365011, 2020).
abdominal aortic aneurysm (4 papers, 2013 to 2019). Enlargement and ballooning of the vessel that supplies arterial blood to the abdomen, pelvis and legs. "A recent study in abdominal aortic aneurysm showed that DCN stabilizes the ECM and inflammation, preventing induced pathology." (PMID 28757161, 2017).
cardiac ischemia (4 papers, 2015 to 2024). "Both BGN and DCN have been shown to act on Toll-like receptors (TLR), which have been implicated in their protective effect against cardiac ischemia as well as in their ability to upregulate tumor suppressor genes facilitating DNA repair mechanisms." (PMID 38786104, 2024). "In our setup, following myocardial ischemia biglycan, decorin and Timp1 mRNA levels are increased in BC−/EC+." (PMID 25875863, 2015). "Mechanistically, DCN might have elicited an imbalanced inflammatory response during cardiac ischemia by suppressing the expression of anti-inflammatory genes." (PMID 34621191, 2021).
diabetic nephropathy (4 papers, 2011 to 2024). "A variant allele of decorin was associated with slower progression of diabetic nephropathy in T1D patients." (PMID 38305779, 2024). "However, in a Mendelian randomization experiment, we associated a decorin eQTL in human fibroblasts with increased risk of diabetic nephropathy, suggesting that species‐ and cell‐type‐specific effects should be considered when therapeutically targeting decorin." (PMID 38305779, 2024). "In advanced stages of diabetic nephropathy, decorin deposition was found in fibrotic areas and colocalized with type I collagen." (PMID 33855203, 2021). "Decorin is also thought to protect against the progression of diabetic kidney disease." (PMID 21494642, 2011). "Decorin, an inhibitor of TGF‐β1 that is upregulated in people with Peyronie's disease, was also upregulated by 650% ± 60% of control values in the kidney tissue of people with diabetic nephropathy compared with healthy kidney tissue." (PMID 33855203, 2021). "In diabetic nephropathy, DCN acts in a protective manner, by reducing ECM accumulation; its absence attracts more mononuclear cells to the sites of insult, while in ocular fibroblasts a combination of suramin and DCN specifically inhibits collagen production." (PMID 28757161, 2017).
dilatation (4 papers, 2011 to 2026). "Decorin expression is typically increased after AMI, and its deficiency has been shown to result in abnormal scar tissue formation and ventricular dilatation and dysfunction." (PMID 40832756, 2026).
fetal growth restriction (4 papers, 2011 to 2024). A fetus that does not grow beyond the 10th percentile of conventionally accepted weight for gestational age. "Placental decorin is decreased during fetal growth restriction." (PMID 38920640, 2024). "Decorin has also been shown to inhibit trophoblast proliferation and migration raising yet another potential mechanism by which altered decorin expression may play a role in the pathogenesis of fetal growth restriction." (PMID 21490795, 2011). "We further discovered that selective DCN overproduction by decidual cells, but not villus mesenchymal cells, was associated with PE with or without fetal growth restriction (FGR), and an elevated level of maternal plasma DCN during the second trimester was a predictive biomarker of PE." (PMID 34638928, 2021).
fibrosis (4 papers, 2017 to 2025). the formation of excess fibrous connective tissue in an organ or tissue in a reparative or reactive process. "Our previous studies revealed that overexpression of decorin inhibited cardiac fibrosis and hypertrophy via transforming growth factor-beta/Smad signaling." (PMID 28290552, 2017). "The application of exogenous decorin decreases fibrosis in lung and kidney fibrosis models." (PMID 35159124, 2022). "Furthermore, cardiac fibrosis was assessed by Masson staining, and the results indicated that there was severe fibrosis in the diabetic hearts, which was attenuated by overexpression of decorin." (PMID 28290552, 2017).
glomerulosclerosis (4 papers, 2011 to 2021). A hardening of the kidney glomerulus caused by scarring of the blood vessels. "It has been reported that the LUM protein and its family member decorin accumulate strongly in the advanced glomerulosclerosis stage of DN." (PMID 34249963, 2021). "Decorin (n = 15, r = 0.64, p<0.05) and glypican-1 (n = 15, r = 0.79, p<0.001) gene expression in the tubulo-interstitium also correlated to presence of global glomerulosclerosis." (PMID 21494642, 2011). "Thus, OTUB1 revealed to be a possible novel regulator during glomerulonephritides, which would facilitate degradation of DCN and enhance the vicious circle characterized by increased TGF-β1 production and matrix deposition in developing glomerulosclerosis." (PMID 22279542, 2012).
Hypertension (4 papers, 2022 to 2025). The presence of chronic increased pressure in the systemic arterial system. "In TAD patients with hypertension decorin, versican core protein and basement membrane-specific heparan sulphate proteoglycan core protein precursor were downregulated." (PMID 36012466, 2022).
Impaired glucose tolerance (4 papers, 2019 to 2025). An abnormal resistance to glucose, i.e., a reduction in the ability to maintain glucose levels in the blood stream within normal limits following oral or intravenous administration of glucose. "Age-related declines in decorin expression have been observed in human fibroblasts, and experimental models show that decorin deficiency is associated with impaired glucose tolerance, increased visceral adiposity, and altered metabolic profiles." (PMID 41441428, 2025). "Loss of decorin in mice caused impaired glucose tolerance in association with increased feed efficiency and altered gene expression in adipose tissue." (PMID 30874564, 2019). "Alongside its role in promoting muscle trophism, improvement of glucose tolerance has also been described for decorin; decorin-knockout mice showed higher leptin levels and impaired glucose tolerance." (PMID 36359757, 2022).
inflammatory breast carcinoma (4 papers, 2021 to 2024). An advanced, invasive breast adenocarcinoma characterized by the presence of distinct changes in the overlying skin. "The lack of decorin in various mouse models of mesenchymal and epithelial neoplasms is permissive for tumorigenesis; conversely, decorin can suppress tumorigenesis, invasion, and metastasis of inflammatory breast cancer." (PMID 35159071, 2022).
lymph node metastasis (4 papers, 2012 to 2023). "This study indicates that high expression of Decorin is associated with lymph node metastasis (p<0.001), higher number of positive lymph nodes (p<0.0001) and worse overall survival (p = 0.01)." (PMID 22363530, 2012). "We also showed that the DCN gene is upregulated regardless of the presence of lymph node metastasis, and it was the only gene significantly associated with the presence of lymph node metastasis in CRC." (PMID 35052821, 2022).
metastatic disease (4 papers, 2020 to 2026). "Based on these observations, we speculate that decreased expression of decorin in liver metastases compared to the primary tumors may reflect the aggressiveness of the metastatic tumor." (PMID 32824864, 2020).
Myocardial fibrosis (4 papers, 2017 to 2020). "Taken together, the diabetic group had developed DCM, while overexpression of decorin attenuated the cardiac dysfunction and myocardial fibrosis." (PMID 28290552, 2017). "In addition, C-terminal truncation of decorin interacts with the connective tissue growth factor, leading to suppression of myocardial fibrosis through down-regulation of cardiac extracellular matrix production." (PMID 32231160, 2020).
Nephropathy (4 papers, 2012 to 2024). A nonspecific term referring to disease or damage of the kidneys. "Furthermore, studies using decorin knockout mice found increased nephropathy/proteinuria in the STZ model." (PMID 38305779, 2024). "In addition, these 106 potential classifiers/biomarkers between TCMR vs. STA are associated with kidney damage (e.g., ATP1B1, CST3, FAH, GSS, HPX and LYZ), tubule injury (e.g., CRYM, GSS, HAGH, HPX and LYZ) and kidney inflammation (e.g., DCN)." (PMID 36814924, 2023).